CLU (clusterin)
Diseases named in the same sentence as CLU in open-access papers (continued):
Sharing a sentence is not in itself a finding about the gene and the disease.
schizophrenia (7 papers, 2019 to 2022). A major psychotic disorder characterized by abnormalities in the perception or expression of reality. "A clusterin polymorphism was associated with schizophrenia in Chinese patients with family history of disease." (PMID 33362763, 2020). "A genome-wide association study found that six immune candidates, namely, DPP4, HSPD1, EGR1, CLU, ESAM, and NFATC3, were associated with schizophrenia." (PMID 35757702, 2022). "The authors hypothesize that clusterin could be playing a neuroprotective role against oxidative stress mediated by TGF-β-signaling, which is associated with schizophrenia pathophysiology." (PMID 30872998, 2019).
α-synucleinopathies (7 papers, 2015 to 2023). "Early studies reported that CLU co-localizes with αSyn in biopsies of patients affected by α-synucleinopathies and that CLU is an αSyn-associated protein in the MES cell line exposed to rotenone." (PMID 33003328, 2020). "Similar to CLU co-localizing with Aβ in the senile plaques, in the case of α-synucleinopathies, CLU co-localizes with cortical Lewy bodies in the brain." (PMID 36850004, 2023). "A recent experimental study suggested that extracellular clusterin blocks the binding site of α-synuclein fibrils, limits the uptake of α-synuclein fibrils by astrocytes, then probably leads to aggregation of clusterin and formation of Lewy bodies, and hence, contributes to the α-synucleinopathy." (PMID 35729600, 2022). "Altogether, APP, CLU, CALCA, and SOD1 may contribute to the α-synuclein-associated synucleinopathy, whereas NEDD4 by posttranslational modification protects against the formation of toxic α-synuclein inclusions." (PMID 36523604, 2022). "Notably, combined measurements of neuronal exosome content of α-synuclein and clusterin improved the predictive test value of a primary intraneuronal α-synucleinopathy in prodromal PD from an alternative proteinopathy (AUC=0.98) or MSA (AUC=0.94)." (PMID 32273329, 2020). "Similarly to the AD pathology, where clusterin co-localizes with Aβ in the senile plaques (reviewed in section “Clusterin in Aβ Metabolism”), in the case of alpha-synucleinopathies, clusterin co-localizes with cortical Lewy bodies (LBs)." (PMID 30872998, 2019).
glioblastoma (6 papers, 2017 to 2025). The most malignant astrocytic tumor (WHO grade IV). "In this context, it is worth mentioning that CLU was identified as one of the hundred most upregulated marker proteins in glioblastoma tumor tissues." (PMID 39627493, 2025). "The findings reveal the dysregulated expression of CLU in many cancers, with a marked increase observed in glioblastoma and lower-grade glioma (LGG)." (PMID 37686218, 2023). "LncEPAT was reported to be a functional oncogene in glioblastoma, and lncEPAT silencing increased the expression of cell aging-associated genes, such as CDKN1A, CLUSTERIN, and DKK1, indicating that lncEPAT exerts a repressive function in glioblastoma cell senescence." (PMID 38228673, 2024). "ER stress also induced co-localization of CLU with inclusions formed by a similar fusion protein (mutant M337 TDP-43 fused at the C-terminus with GFP; TDP-43M337V-GFP) in U251 human glioblastoma cells." (PMID 29115989, 2017).
hippocampal atrophy (6 papers, 2019 to 2024). "Nonetheless, additional research is required to validate these findings and elucidate the underlying mechanisms connecting clusterin, hippocampal atrophy, and cognitive function." (PMID 37941999, 2023). "Additionally, higher plasma clusterin levels have been associated with increased hippocampal atrophy and increased rate of clinical progression, suggestive of clusterin as a promising biomarker." (PMID 30872998, 2019). "Specific glycans on clusterin were decreased in abundance in AD patients with high hippocampal atrophy relative to those with low hippocampal atrophy, analysed using LC-MS/MS analysis." (PMID 31484367, 2019). "Understanding the importance of glycosylated CLU proteins is particularly important since several studies have identified plasma CLU as a promising marker for AD71; higher plasma CLU levels are associated with increased hippocampal atrophy and increased rate of clinical progression." (PMID 36329114, 2022).
Huntington disease (6 papers, 2009 to 2022). Huntington disease (HD) is a rare neurodegenerative disorder of the central nervous system characterized by unwanted choreatic movements, behavioral and psychiatric disturbances and dementia. "Moreover, RNA sequence analysis of human Huntington’s disease brain showed CLU as one of the top differentially expressed genes." (PMID 36009409, 2022). "Both CLU and TF are involved in oxidative stress response, apoptosis, and DNA damage response (DDR) and have been reported to be involved in Huntington’s disease pathogenesis." (PMID 36009409, 2022).
injury (6 papers, 2009 to 2020). Damage inflicted on the body as the direct or indirect result of an external force, with or without disruption of structural continuity. "CLU, also known as clusterin, is a complement inhibitor that appears to have a neuroprotective effect in response to tissue damage, and its expression is upregulated following acute head injury." (PMID 31915578, 2020). "We have previously identified other proteins such as transferrin, clusterin, serum amyloid protein, hemoglobin α-2, and α-2 HS-glycoprotein that were elevated in patients with acute lung injury; however, these proteins were not differentially abundant in this study." (PMID 19432985, 2009).
lymphoma (6 papers, 2015 to 2025). A malignant (clonal) proliferation of B- lymphocytes or T- lymphocytes which involves the lymph nodes, bone marrow and/or extranodal sites. "Clusterin positively correlated with lymphocytes, with previous studies reporting an association between Clusterin and lymphoma pathogenesis." (PMID 38040779, 2023). "A recent study evaluated the serum clusterin levels in canine multicentric lymphoma and found that dogs with lymphoma had lower clusterin levels than healthy dogs, dissimilar to our results." (PMID 35765478, 2022). "This study observed high serum clusterin or apolipoprotein J in canine lymphoma, especially the B-cell subtype." (PMID 35765478, 2022). "Consequently, the role of clusterin in specific lymphoma subtypes in dogs needs to confirm in future studies." (PMID 35765478, 2022). "CLU expression may occur in malignant lymphoma, for instance, including HL." (PMID 36077307, 2022). "Additionally, clusterin (CLU) expression was also upregulated in both the GFP+ samples, particularly in replicates 1, 2 and 3, and the lymphomas." (PMID 40627772, 2025). "In another study, haptoglobin (Hp), α2 macroglobulin, α-antichymotrypsin, inter-α-trypsin inhibitor, and clusterin were identified in dog sera with a lymphoma versus a non-lymphoma group by two-dimensional electrophoresis (2DE) and tandem MS." (PMID 35765478, 2022). "Clusterin (CLU), in its cytoplasmic secretory form (sCLU), has the unique property in mediating chemoresistance to numerous unrelated anticancer agents and its presence has been observed in a variety of solid tumors and lymphoma." (PMID 25884382, 2015).
tauopathies (6 papers, 2020 to 2025). "We found that loss of CLU was associated with the aggravated accumulation of pathological tau and behavioral abnormalities in our mouse model of tauopathy." (PMID 33261653, 2020). "Given that tau is abnormally hyperphosphorylated in AD and other tauopathies, we next evaluated the pattern of phosphorylation at different epitopes in cortex and hippocampus of CLU WT-TauP301L and CLU KO-TauP301L animals." (PMID 33261653, 2020). "We also found that CLU co-localized with tau deposits in human tauopathy cases and that direct interaction of CLU and tau in a cell-free system led to a dramatic reduction of the tau filament formation." (PMID 33261653, 2020). "We observed CLU co-localization with tau aggregates in AD and primary tauopathies and CLU levels were upregulated in response to tau accumulation." (PMID 33261653, 2020). "Interestingly, clusterin appears to directly affect tau pathology, as it colocalizes with pathological tau accumulations in tauopathies, and knockout of clusterin in tau transgenic mice exacerbates pathology." (PMID 40113250, 2025). "Importantly, our study is the first to show a significant increase in CLU levels in primary tauopathies compared to controls, suggesting that CLU upregulation occurs not only in the presence of amyloid plaques but also tau pathology." (PMID 33261653, 2020). "Clusterin did not correlate with UPDRS or MoCA scores in tauopathies (R2 = 0.0022 and 0.0245, respectively)." (PMID 33826157, 2021). "Moreover, CLU immunoreactivity was present in many NFT-bearing neurons in both primary and secondary tauopathies suggesting tau-specific changes in CLU expression." (PMID 33261653, 2020).
asthma (5 papers, 2017 to 2023). "The possible relationships between osteopontin, clusterin, and asthma control determinants were also evaluated." (PMID 29200898, 2017). "Clusterin is a sensitive cellular biosensor of oxidative stress which is an important factor in the pathophysiology of asthma and also maternal asthma during pregnancy." (PMID 29200898, 2017). "Clusterin is also related to asthma, a chronic inflammatory airway disorder." (PMID 37717073, 2023). "Osteopontin and clusterin emerged as asthma biomarkers; however, their circulating levels during pregnancy are unknown yet." (PMID 29200898, 2017). "IL-6, RANTES, Clusterin, MIG, BLC and MIP-1a/b have been found to exhibited raised levels in asthma." (PMID 34516405, 2021). "Circulating clusterin concentration was found to be elevated in patients with severe asthma, and it showed an inverse correlation with lung function; however, clusterin was considered an indicator of oxidative stress rather than a protective factor." (PMID 29200898, 2017). "In the present study, we aimed to investigate osteopontin and clusterin levels in asthma and asthmatic pregnancy in comparison with healthy nonpregnant control subjects and healthy pregnant women." (PMID 29200898, 2017). "Asthma itself also did not influence circulating clusterin level, as ANP and HNP groups had similar results (109.2 [95.59–116.3] versus 108.8 [97.94–115.3] μg/mL, p = 0.8730)." (PMID 29200898, 2017).
autoimmune disease (5 papers, 2018 to 2024). A disorder resulting from loss of function or tissue destruction of an organ or multiple organs, arising from humoral or cellular immune responses of the individual to their own tissue constituents. "CR1 and CLU gene are related to thymus function which could potentially cause an autoimmune disorder." (PMID 30666269, 2018). "The authors summarized that these results identify CLU as a new molecule involved in apoptotic cell efferocytosis and suggest a protective role for CLU in inflammation and autoimmune diseases." (PMID 39684771, 2024). "Clusterin is a multifaceted protein functioning at the crossroads of inflammation and autoimmune diseases." (PMID 31708932, 2019). "PICALM, PVRL2, PVR, and CLU have shown to be related to systemic, an autoimmune disease characterized by vascular injury and debilitating tissue fibrosis." (PMID 30666269, 2018). "Clusterin, as an extracellular chaperon, exhibits the characteristics of innate immune system receptors and facilitates such clearance, thus providing protection against the development of autoimmune disease." (PMID 32764517, 2020).
brain ischemia (5 papers, 2009 to 2025). Diminished or absent blood supply to the brain caused by obstruction (thrombosis or embolism) of an artery resulting in neurologic damage. "Our study demonstrates elevated levels of clusterin and pro-inflammatory cytokines in the cerebral ischemia-reperfusion mice, as shown in previous studies." (PMID 32084011, 2020). "Therefore, clusterin is a crucial indicator of the status of neuroinflammation induced by repeated cerebral ischemia-reperfusion." (PMID 32084011, 2020). "Clusterin is a biomarker for the immune response that follows cerebral ischemia-reperfusion." (PMID 32084011, 2020). "Treatment with 50-100 mg/Kg baicalin for 7 days after cerebral ischemia-reperfusion significantly restored normal plasma levels of TMA, TMAO, and clusterin." (PMID 32084011, 2020). "Repeated cerebral ischemia-reperfusion significantly increased plasma levels of trimethylamine (TMA), trimethylamine-N-oxide (TMAO), and clusterin (a neuroinflammation biomarker)." (PMID 32084011, 2020).
breast tumor (5 papers, 2007 to 2023). "Treatment of breast tumor cells with 100 or 500 nM antisense clusterin ODN decreased clusterin compared with cells treated with mismatch control ODN." (PMID 18078515, 2007). "We also evaluated the effect of cytotoxic treatment on the level of clusterin expression in breast tumor cell lines because this has been shown to be highly upregulated in various tissues undergoing apoptotic cell death." (PMID 18078515, 2007).
cervical cancer (5 papers, 2015 to 2021). A primary or metastatic malignant neoplasm involving the cervix. "The overexpression of CLU was detected in metastatic ovarian and cervical cancer compared with matched normal tissues." (PMID 26988917, 2016).
dry eye (5 papers, 2015 to 2024). "We recently reported that the natural tear glycoprotein CLU (clusterin), a molecular chaperone and matrix metalloproteinase inhibitor, seals and heals epitheliopathy in mice subjected to desiccating stress in a model of aqueous-deficient/evaporative dry eye." (PMID 36674497, 2023). "CLU deficiency resulted in greater ocular surface damage due to desiccating stress in knockout mice subjected to the air-draft-plus-scopolamine protocol, a model of mixed aqueous-deficient and evaporative dry eye." (PMID 36674497, 2023). "Evidence is presented herein supporting the potential of the natural homeostatic glycoprotein CLU (clusterin) as a novel therapeutic for the treatment of dry eye." (PMID 33374364, 2020). "Evidence is presented herein supporting potential of the natural homeostatic glycoprotein CLU as a novel therapeutic for the treatment of dry eye." (PMID 33374364, 2020). "Expression of CLU in the ocular surface epithelia is dramatically reduced in human inflammatory disorders that manifest as severe dry eye." (PMID 26402857, 2015). "Collectively, these results suggest that down-regulation of CLU expression at the ocular surface subjected to desiccating stress in dry eye is due to activation of the inflammatory cascade." (PMID 26402857, 2015). "Additionally, it has been reported that clusterin interacts with MMP-9 to reorganize the tissue by modulating ECM in corneal epithelial cells of the dry eye and in immune cells such as monocytes and macrophages in vitro." (PMID 28767729, 2017). "Similarly, we showed recently that both CLU protein and mRNA levels in the ocular surface epithelia are reduced by ~30% when desiccating stress is induced in a preclinical mouse model for dry eye." (PMID 26402857, 2015).
esophageal squamous cell carcinoma (5 papers, 2007 to 2020). Esophageal squamous cell carcinoma (ESCC) is a type of esophageal carcinoma (EC) that can affect any part of the esophagus, but is usually located in the upper or middle third. "Serum clusterin had an optimal diagnostic cut-off point (serum clusterin concentration = 335.5 μg/mL) for esophageal squamous cell carcinoma with sensitivity of 71.26% and specificity of 77.94%." (PMID 25574066, 2014). "By our calculation, serum clusterin had an optimal diagnostic cut-off point (serum clusterin concentration = 335.5 μg/mL) for esophageal squamous cell carcinoma with sensitivity of 71.26% (95% CI, 60.57% to 80.46%) and specificity of 77.94% (95% CI, 70.03% to 84.59%)." (PMID 25574066, 2014). "Several studies show greatly reduced expression of CLU in tumors compared with normal tissue, including testicular tumor, von Hippel-Lindau (pVHL)-defective renal tumor, esophageal squamous cell carcinoma." (PMID 17989776, 2007).
fibrosis (5 papers, 2017 to 2025). the formation of excess fibrous connective tissue in an organ or tissue in a reparative or reactive process. "In conclusion, upregulation of clusterin in the fibrotic liver can be a protective response whatever the cause of fibrosis, and clusterin reduces hepatic fibrosis by inhibiting HSC activation and Smad3 signaling pathways." (PMID 31739636, 2019).
glomerulopathy (5 papers, 2016 to 2024). "CLU, a secreted protein which originates from multiple segments of the renal tubule as well as mesangial cells, increased in urine on days 16, 21, and 28 in anti-Fx1A-treated animals, consistent with previous rat models of glomerulopathy." (PMID 35622875, 2022).
liver cancer (5 papers, 2020 to 2025). An epithelial or non-epithelial malignant neoplasm that arises from the liver. "However, increased expression of CLU in tumor tissues has been linked to worse prognosis in several investigations of liver cancer." (PMID 36685863, 2022). "Some studies suggested a role of clusterin in liver cancer development." (PMID 33798093, 2021). "Furthermore, decreased CLU expression correlated with poor OS (p < 0.001), PFS (p < 0.001), and relapse-free survival (RFS) (p = 0.0011) in patients with hepatic cancer." (PMID 36685863, 2022). "Based on these results, to investigate whether clusterin activates AMPK in vitro, we treated Huh7 cells, a liver cancer cell line, with purified human clusterin." (PMID 33060605, 2020).
meningioma (5 papers, 2014 to 2023). A generally slow growing tumor attached to the dura mater. "Clusterin/apolipoprotein J (CLU) is a secreted chaperone that has been reported as a proteomic marker associated with meningiomas." (PMID 37627098, 2023). "Western blot analyses of three differentially expressed targets proteins; apolipoprotein E, ceruloplasmin and clusterin were carried out using a subset of healthy control and meningiomas samples (MGI, MGII and MGIII)." (PMID 25413266, 2014). "Western blot results indicated up-regulation of Apo E, CLU and CP in meningioma patients compared to the healthy controls (p < 0.005 in a Mann Whitney U-test)." (PMID 25413266, 2014). "In Meningiomas, the protein CLU was found to be upregulated when compared to controls." (PMID 34055594, 2021). "Furthermore, the genes CLU and PTN, which are known to be highly expressed in other neoplastic cells, were also found to be commonly expressed in meningioma neoplastic cells." (PMID 37880655, 2023). "For the meningioma tissue samples, we observed overexpression of VIM, CST3 and CLU." (PMID 34055594, 2021).
osteoarthritis (5 papers, 2014 to 2023). A noninflammatory degenerative joint disease occurring chiefly in older persons, characterized by degeneration of the articular cartilage, hypertrophy of bone at the margins and changes in the synovial membrane. "Given the significant potential of clusterin as a biomarker of osteoarthritis (OA), a more detailed analysis of its complex network in an inflammatory environment, specifically in the context of OA, is required." (PMID 37033956, 2023). "The involvement of CLU in joint degenerative diseases has been recently hypothesized." (PMID 32516132, 2020).